INS (insulin)
Diseases named in the same sentence as INS in open-access papers (continued):
Sharing a sentence is not in itself a finding about the gene and the disease.
pancreatic cancer (284 papers, 1990 to 2026). "There was also heterogeneity by underlying pancreatic condition, with the greatest early insulin initiation in pancreatic cancer (HR 19.48 [95% CI 17.37–21.84]) and chronic pancreatitis subtypes (HR 13.82 [95% CI 13.06–14.62])." (PMID 39762966, 2025). "We newly identify patients with autoimmune liver diseases, carriers of BRCA gene mutations, patients co-infected with hepatitis B and C and those diabetics requiring insulin as at high risk of pancreatic cancer." (PMID 40584837, 2025). "Metformin, a first-line T2DM treatment, reduces the risks of liver and bile duct cancers, while insulin use is associated with a lower pancreatic cancer risk." (PMID 40597094, 2025). "A systematic review and meta-analysis also indicated that insulin use is associated with an increased risk of pancreatic cancer." (PMID 40356973, 2025). "Key factors associated with NOD in the context of pancreatic cancer include age, a family history of pancreatic cancer, previous episodes of pancreatitis or cholecystitis, weight loss, and a rapid increase in blood glucose levels or the need for insulin." (PMID 40125183, 2025). "Olfactory receptors were reported to be highly expressed in the pancreas and regulate insulin secretion, and the olfactory transduction pathway was found as one of the most significant pathways associated with risk of pancreatic cancer." (PMID 38750539, 2024). "A reduction in abdominal fat showed a metabolic improvement in glucose tolerance and insulin sensitivity in pancreatic cancer risk." (PMID 39766104, 2024). "It has also found a causal link between genetically increased fasting insulin levels and an increased risk of pancreatic cancer." (PMID 38831236, 2024). "Metformin has been shown to improve the prognosis of pancreatic cancer by inhibiting the mTOR pathway, leading to decreased energy consumption and cell growth and increasing insulin sensitivity, causing decreased blood glucose levels." (PMID 38611003, 2024). "Epidemiological studies also revealed a link between elevated levels of insulin and an increased risk of pancreatic cancer." (PMID 38397072, 2024). "The analysis showed a correlation between an elevated risk of pancreatic cancer and genetically predicted pancreatic fat, high-density lipoprotein, BMI particles, BMI, fasting insulin level, Crohn illness, intestinal flora, and C-reactive protein." (PMID 39465831, 2024). "By contrast, insulin and SUs demonstrated a stronger association with increased pancreatic cancer risk in DM patients, with variations noted across ethnic populations." (PMID 39595655, 2024). "The role of insulin in other malignancies was established with a meta-analysis reporting an increased risk for colorectal and pancreatic cancers with higher levels of insulin and C-peptide." (PMID 37455285, 2023). "Conversely, the use of insulin secretagogues was associated with a moderately elevated risk of pancreatic cancer." (PMID 37481610, 2023). "Overall, biguanide and thiazolidinedione use carried no risk, or potentially lower risk of some cancers, while insulin secretagogue and insulin use were associated with increased pancreatic cancer risk." (PMID 37481610, 2023). "Fatty infiltration of the pancreas or “fatty pancreas”, which is synonymous with fatty degeneration in the pancreas, has recently been found to affect pancreatic insulin secretion and potentially act as a risk factor for pancreatic cancer." (PMID 36900085, 2023). "First, dietary fiber intake can influence insulin insensitivity or insulin resistance pathways, which are associated with the etiology of pancreatic cancer." (PMID 37299507, 2023). "The inconsistent association between insulin secretagogues and colorectal cancer and biguanides and pancreatic cancer, which varied by study design, underscores the need to interpret results cautiously." (PMID 37481610, 2023).
pancreatic cancer (continued). "Decreased adiponectin enhances the susceptibility to pancreatic cancer development and is associated with pancreatic cancer growth and dissemination by inhibiting the action of insulin, which can activate PI3K/AKT signaling." (PMID 37444627, 2023). "Opposing associations with different cancer sites within a medication class were also evident; insulin use was associated with a higher risk of liver and pancreatic cancers but a lower risk of breast and prostate cancers." (PMID 37481610, 2023). "Fifth, SSB consumption is related to insulin release, which is known to be associated with pancreatic cancer." (PMID 35463371, 2022). "In the past decades, it has been generally accepted that insulin was a risk factor in many types of cancer, including colorectal cancer, breast cancer, liver cancer, and pancreatic cancer." (PMID 35252207, 2022). "Aberrant carcinoma of the pancreas has been shown to lead to deficient or uncontrolled hormone production, including insulin that regulates blood sugar levels." (PMID 34907162, 2021). "Many studies have shown that metformin can reduce the risk of cancer, including breast, colon, liver, and pancreatic cancers, and improve outcomes over those obtained with other antidiabetic treatments (sulfonylurea, insulin) in diabetic patients." (PMID 32825834, 2020). "There are suggestions that insulin therapy, sulphonylurea therapy, and sitagliptin or exenatide can confer an increased risk of pancreatic cancer." (PMID 31687406, 2019). "Investigation of the literature highlighted by MELODI informs us that increased insulin secretion is associated with some forms of pancreatic cancer." (PMID 29342271, 2018). "Isaksson16 demonstrated that defects in insulin activity and glucose transport contributed to pancreatic cancer-associated insulin resistance on cellular level." (PMID 29057932, 2017). "In contrast, each SD increase in fasting insulin was associated with an increased risk of pancreatic cancer (OR = 1.66, 95% CI = 1.05 to 2.63), with little evidence for between-study heterogeneity." (PMID 28954281, 2017). "Our results suggest that increases in BMI and fasting insulin are causally associated with an increased risk of pancreatic cancer." (PMID 28954281, 2017). "There was also evidence that genetically increased fasting insulin levels were causally associated with an increased risk of pancreatic cancer (OR = 1.66, 95% CI = 1.05 to 2.63, per SD [44.4 pmol/L])." (PMID 28954281, 2017). "For fasting insulin, we observed a 66% increased risk of pancreatic cancer per SD increase (44.4 pmol/L), although the strength of the association was marginal (P = .03), especially if the number of comparisons is considered." (PMID 28954281, 2017). "A potential causal relationship between increased insulin and cancer risk using genetic instruments has also been reported for endometrial cancer and pancreatic cancer." (PMID 28594918, 2017). "Other have reported decreased miR-122 expression in pancreatic cancer compared to healthy tissues and a positive association between miR-122 mRNA levels in islets and insulin mRNA biosynthesis." (PMID 29258547, 2017). "Our results support higher BMI as a causal risk factor of pancreatic cancer, as well a potential causal role of higher insulin, in particular among men." (PMID 28954281, 2017). "A study in 2009 with 62,809 patients compared cancer risk in patients on different kinds of diabetic therapies and found that insulin therapy increased the risk of pancreatic cancer compared to metformin therapy." (PMID 25426078, 2014). "MIF is up-regulated in patients with pancreatic cancer and causes dysfunction of insulin secretion in β-cells." (PMID 24708788, 2014). "A meta-analysis of reported new use of insulin or insulin glargine was associated with an increased risk of pancreatic cancer, but with a decreased risk of colorectal cancer." (PMID 24924771, 2014).
pancreatic cancer (continued). "In the present study, we demonstrated that pancreatic cancer progression is associated with changes in insulin signalling pathways that underlie cell survival, proliferation and viability." (PMID 25373319, 2014). "Multiple epidemiological studies have drawn a positive link between high levels of insulin and an increased risk of pancreatic cancer." (PMID 25373319, 2014). "Epidemiologic studies indicated that HbA1c, FPG, and insulin levels were proportionally associated with pancreatic cancer risk, which was the highest after a 10 years of followup." (PMID 23476808, 2013). "Pancreatic cancer risk was higher in the insulin users compared with the non-insulin users in the crude model (RR = 2.55, 95% CI 1.04–6.26, P = 0.042), but was not statistically significant after fully adjusted (RR = 2.73, 95% CI 0.93–7.99, P = 0.067)." (PMID 23308218, 2013). "Individuals with elevated fasting glucose and glycated haemoglobin (HbA1c) levels, or with higher c-peptide or insulin levels have a two to four-fold increase in the risk of pancreatic cancer." (PMID 23663483, 2013). "Recently, multiple epidemiological studies and meta-analysis revealed that pancreatic cancer risk was increased among new users of insulin or insulin glargine." (PMID 24171174, 2013). "Further support for this mechanisms is lent by epidemiologic studies in which prediagnostic elevations in fasting serum glucose, post-load plasma glucose, and fasting serum insulin have been associated with an elevated risk of pancreatic cancer." (PMID 17533398, 2007). "Interestingly, in this study pancreatic cancer was more often associated with the change in DM medication or insulin as the first medication (32% vs. 12%)." (PMID 40299428, 2025). "A recent retrospective cohort study similarly showed that GLP-1R agonist use was associated with a lower risk of pancreatic cancer compared with use of several other antihyperglycemic drugs, including insulin, metformin, DPP4 inhibitors, SGLT2 inhibitors, sulfonylurea, or thiazolidinediones (TZDs)." (PMID 41178720, 2025). "Interestingly, the mechanisms underlying the tumorigenesis of insulin in pancreatic cancer have been recently shown." (PMID 38831236, 2024). "According to prospective follow-up studies conducted in Taiwan, insulin use together with smoking may significantly increase the risk of mortality from hepatocellular carcinoma, bladder cancer, and pancreatic cancer in patients with T2D, among others." (PMID 38969701, 2024). "The MR approach, under specific assumptions, has proven to be effective in studying the potential causes of pancreatic cancer, consistently showing the causal relationship between BMI, fasting insulin, and low-density lipoprotein levels with pancreatic cancer risk." (PMID 38425433, 2024). "On the other hand, elevated risk of pancreatic cancer was observed with insulin secretagogue use (n = 5; RR = 1.26; 95% CI = 1.01–1.57), and elevated risks of liver (n = 7; RR = 1.74; 95% CI = 1.08–2.80) and pancreatic cancers (n = 8; RR = 2.41; 95% CI = 1.08–5.36) were observed with insulin use." (PMID 37481610, 2023). "Among these, pancreatic cancer showed the highest risk of insulin requirement." (PMID 36831436, 2023). "Specifically, the risk of requiring insulin treatment after gallbladder and pancreatic cancer development was higher in the first year after cancer diagnosis, whereas hematologic cancer showed a relatively lower risk of requiring insulin treatment after cancer development during the three years." (PMID 36831436, 2023). "Additionally, a Mendelian randomization study utilizing genome-wide data revealed a correlation between genetically elevated fasting insulin levels and an increased risk of pancreatic cancer." (PMID 37654164, 2023). "Interestingly, we also found a clear increase in the risk of requiring insulin treatment in cancer survivors, except for patients with pancreatic cancer." (PMID 36831436, 2023).
pancreatic cancer (continued). "Increased expression of HIF-1A, gene encoding hypoxia-inducible factor-1 alpha, the master regulator of oxygen sensing and metabolic regulation in cells, and INS encoding insulin further indicate that fibroblasts assume a pro-metastatic role and are complicit in pancreatic cancer progression." (PMID 35565326, 2022). "However, rather than being a risk factor for developing cancer, it is believed to be caused by the presence of the pancreatic tumor itself, as surgical removal of the cancer significantly decreases insulin resistance." (PMID 36355178, 2022). "Two of them (III3 and IV2) had died from other causes (pancreatic cancer and cancer of unknown primary): One is treated with insulin and metformin (III1), and one is treated with diet only (V3)." (PMID 35406570, 2022). "Pancreatic cancer induces hormonal imbalance, triggering the hypo- and hypersecretion of insulin, which may cause rapid changes in serum glucose, impinging on the consciousness of patients and their appetite conditions." (PMID 36554049, 2022). "Taken together, we hypothesized that the primary cause of poor prognosis of pancreatic cancer, at least in our study, was metabolic disorders caused by inadequate insulin secretion, which was fueled by neuroendocrine aberration." (PMID 34090418, 2021). "In another study, the administration of pioglitazone, insulin and its analogues to the diabetic patients were found to be associated with increased risk of pancreatic cancer by 45%, hepatic cancer by 32% and pulmonary cancer by 18% as compared to the non-users." (PMID 34535145, 2021). "Growing reports have suggested that insulin may increase the risk of certain cancers, such as prostate, rectal, breast and pancreatic cancers." (PMID 33250766, 2020). "In addition, we have also found using MR that elevated fasting levels of insulin are causally associated with pancreatic cancer (unpublished data at time of article press)." (PMID 29342271, 2018). "Our results suggest a causal role of BMI and fasting insulin in pancreatic cancer etiology." (PMID 28954281, 2017). "A plausible explanation for a reduced risk of pancreatic cancer with moderate alcohol intake may be that moderate intake lowers the levels of fasting insulin, which is related to the decreased risk of pancreatic cancer." (PMID 28067765, 2017). "In vitro studies indicate that adrenomedullin impairs glucose-stimulated insulin secretion in β-cells, and adrenomedullin overexpression in mouse pancreatic cancer tissues is associated with increased glucose intolerance suggesting that adrenomedullin is an important mediator of cancer-induced DM." (PMID 25426078, 2014). "Metformin appears to reduce risk for pancreatic cancer and improve survival in diabetics with pancreatic cancer primarily by decreasing insulin/IGF signaling, disrupting mitochondrial respiration, and inhibiting the mammalian target of rapamycin (mTOR) pathway." (PMID 25426078, 2014). "High glucose levels and low insulin sensitivity characteristic of both obesity and early-stage diabetes may lead to pancreatic cell damage and subsequently, an increased risk of pancreatic cancer." (PMID 18307811, 2008). "An abnormal insulin and glucose profile is related to increased risk of pancreatic cancer." (PMID 12659113, 2003). "Thus, 25(OH)D may be linked to endocrine pancreatic function and inhibit pancreatic cancer development through regulation of insulin synthesis, binding, and responsiveness." (PMID 28969079, 2017). "Thus, the diffuse distribution of relative small islets might be evolutionarily conserved to prevent excessive local insulin concentrations that might increase the risk of pancreatic cancer." (PMID 23798995, 2013). "Considering that a pancreatic malignancy can produce an impairment of insulin secretion, deteriorating glycemic control, the prescription of insulin could be the consequence, rather than the cause, of an underlying (and still undiagnosed) pancreatic cancer." (PMID 23209929, 2012).
pancreatic cancer (continued). "Both varieties exhibited antiproliferative activity against BxPC-3 pancreatic cancer cells (IC50: 289.2-356.8 μg/mL) and significantly improved the glucose uptake in insulin-resistant HepG2 cells." (PMID 42195899, 2026). "Compared to insulin, GLP-1RA medications were associated with a significantly lower risk of liver cancer (HR: 0.47, 95% CI: 0.27-0.82) and pancreatic cancer (HR: 0.23, 95% CI: 0.11-0.51)." (PMID 41749007, 2026). "Type 1 DM (T1DM) is characterized by the complete loss of insulin production, mostly due to autoimmune-dependent elimination of the islet cells; surgical removal of the pancreas in cases of pancreatic cancer can also lead to insulin dependence." (PMID 40803202, 2025). "In that study, the combination of GLP-1R therapy and insulin predicted a greater risk for pancreatic cancer compared with GLP-1R monotherapy, consistent with a reported tumor-promoting role of insulin in preclinical pancreatic cancer models." (PMID 41178720, 2025). "A cohort study investigating cancer risks in insulin users across five countries found that, except among Norwegians, pancreatic cancer was reported as the most common cancer." (PMID 40356973, 2025). "The results showed that three genes—NANOG, CK19, and INS—were significantly elevated in patients with pancreatic cancer compared to healthy controls." (PMID 40699634, 2025). "Insulin can directly induce PD-L1 expression in pancreatic cancer cells via the insulin receptor-A and/or IGF-receptor-induced MAPK/ERK signaling pathway." (PMID 41465460, 2025). "The Sorbin and SH3 domain containing 1 (SORBS1), a protein linked to insulin signaling CBL interaction, was investigated for its role in pancreatic cancer apoptosis." (PMID 40918460, 2025). "We found that the expression of genes characteristic of early stem cells, NANOG (p = 0.03), and the expression of genes encoding insulin and cytokeratin 19 (INS p = 0.02, CK19 p = 0.005) were increased in pancreatic cancer patients." (PMID 40699634, 2025). "As previously observed in smaller datasets, we observed greater early insulin initiation in people with type 3c diabetes compared to T2D,9, 16, 29, 30 particularly in people with chronic pancreatitis or pancreatic cancer." (PMID 39762966, 2025). "For example, the human insulin promoter was used as a basis for the development of synthetic human insulin super-promoter (SHIP1) for pancreatic cancer gene therapy." (PMID 39682712, 2024). "In contrast, pancreatic tumors originating from endocrine cells are uncommon, and typically exhibit excessive hormone secretion, most commonly insulin or glucagon." (PMID 39200178, 2024). "The analysis of keyword centrality conducted using CiteSpace revealed that ‘pancreatic cancer’ (0.44), ‘in-vivo’ (0.21), ‘cancer’ (0.16), ‘expression’ (0.19), and ‘insulin secretion’ (0.15) were among the keywords with the highest centrality." (PMID 39099697, 2024). "Exosomes derived from pancreatic cancer cells induce insulin resistance in skeletal muscles, as extrapolated from observations that such exosomes inhibit insulin-PI3K-Akt signaling in C2C12 myotubes, thereby disrupting GLUT4 uptake." (PMID 39596226, 2024). "Increased insulin and leptin levels have been previously observed in diet-induced obese mice with pancreatic cancer." (PMID 39599705, 2024). "For instance, the use of insulin secretagogues showed a more prominent effect on liver and pancreatic cancers in case–control studies than in cohort studies." (PMID 37481610, 2023). "Here we report that in the context of hyperinsulinemic conditions [a common phenomenon in PDAC, either in the setting of new onset or long-standing diabetes], heparanase augments insulin-INSR signaling cascade in pancreatic tumor cells." (PMID 38078007, 2023). "In the pancreas it is important in islet insulin secretion, growth of pancreatic cancer cells and in pancreatitis." (PMID 37138671, 2023).